MYC (MYC proto-oncogene, bHLH transcription factor)
Diseases named in the same sentence as MYC in open-access papers (continued):
Sharing a sentence is not in itself a finding about the gene and the disease.
cancer (continued). "As c-MYC overexpression has been extensively reported as a feature conferring chemoresistance to cancer cells, we can hypothesize that the reduced c-MYC protein levels observed after METTL3 silencing could represent the determinant allowing sensitization to cisplatin treatment." (PMID 34530916, 2021). "In addition to CDK7, higher activity of CDK9i in cancers with deregulated MYC is already known." (PMID 34637026, 2021). "However, in all instances, MYC-dependent cancers were used as model systems and resistance was universally conferred through reactivation of MYC expression, despite being mediated by different mechanisms, such as activation of Wnt signaling, co-regulation by GLI220, or phosphorylation of BRD419." (PMID 33712563, 2021). "Thus, targeting the MYC oncogene could be a potential therapeutic strategy for MYC-dependent cancers such as KRAS-mutant CRC." (PMID 34944853, 2021). "Moreover, it has been shown that MYC proteins and the mTOR pathway cooperate with each other at the transcription and translation levels, respectively, to elevate overall protein synthesis rate, leading to increased cell proliferation and cancer progression." (PMID 34565342, 2021). "However, in addition to the oncogenic protein-coding genes, the region 8q24.21 is a host to numerous lncRNAs associated with various cancers and with functions that are independent of MYC." (PMID 33499210, 2021). "Therefore, therapies targeting SQLE may be a promising strategy in the treatment of certain MYC-driven cancer." (PMID 33791309, 2021). "Our finding that the rCRE-MYC promoter interaction is dependent on 3D genome architecture suggests that the frequent looping observed in 8q24.21 may contribute to the failure in identifying MYC eQTLs in prostate and other cancer types." (PMID 33741908, 2021). "Thus, controlling the expression of MYC is considered as an approach for targeted cancer treatment." (PMID 34440124, 2021). "Importantly, ZHX2 and MYC share coamplification in most cancer types observed." (PMID 34779768, 2021). "Hence, the downregulation of ABR, PREX1, DOCK2, and DOCK4 promotes cancer development and leads to a poor prognosis by activating MYC and DNA repair signaling pathways in NSCLC, and further in vitro and in vivo studies are necessary to further confirm their association." (PMID 34783629, 2021). "Hence, MYC activation seems to constitute the main inducer of most molecular hallmarks of cancer." (PMID 35582389, 2021). "Interestingly, to date, only four SNPs have been located within the MYC locus and none of these SNPs are associated with cancer." (PMID 33499210, 2021). "Likewise, CCND1 (cyclin D1) is amplified or overexpressed in cancer and may cooperate with MYC to promote transformation." (PMID 33996588, 2021). "Hence, selectively inhibiting DUBs that stabilize MYC could be an attractive strategy for the treatment of MYC-driven cancers." (PMID 33546726, 2021). "Similarly, abundant studies demonstrated that E2F4, STAT1, MYC, ERG, and NFYB may play an important role in the pathogenesis and progression of various cancers, including OSCC, and the underlying mechanism may be related to dysregulated lncRNA." (PMID 32923393, 2020). "Therefore, PVT1, in conjunction with or instead of MYC might be the cancer driver gene in this setting." (PMID 32877461, 2020). "Thus, failed Pc-dependent autorepression and/or defective repression of super-enhancers via CTCF could further elevate MYC to promote cancer progression." (PMID 32527935, 2020). "Thus, suggesting that the regulation of oncogenic c-MYC harnessed to treat cancer patients." (PMID 32604971, 2020).
cancer (continued). "Additionally, the oncogenic transcription factor MYC can upregulate the mRNA levels of heteronuclear ribonucleoproteins (hnRNP) A1 and A2 in a variety of malignant tumors, and hnRNPs facilitate the synthesis of M-type pyruvate kinase (PKM2), thus strengthening the Warburg effect." (PMID 32653017, 2020). "Thus, by appropriately adjust the expression level of these hub genes, we may easily affect their downstream genes, for example, MYC or MAPK gene family in some important signaling pathways to further influence cancer growth." (PMID 32766227, 2020). "However, as all studies to date have focused on the developmental role of the protein, the significance of MYC inhibition in adult cellular physiology is less established, and so the consequences of MYC inhibition for normal tissues during cancer therapy are hard to predict." (PMID 31636382, 2020). "Therefore, DPY30 and H3K4 methylation were suggested as potential epigenetic pathways that could be therapeutically targeted in MYC-dependent cancers." (PMID 33302406, 2020). "However, cancers are highly dependent on the activity of c-MYC to sustain mRNA translation." (PMID 32759815, 2020). "EPIC1 has been found to promote the cell resistance to iBET762 (bromodomain and extra-terminal motif inhibitor) and JQ-1 via activation of MYC transcriptional activity in cancer cells, suggesting that EPIC1 could be useful as a predictive lncRNA for BET inhibitors." (PMID 32322669, 2020). "Moreover, overexpression of MYC confers survival benefit to cancer cells by increasing the synthesis of biomolecules and energy production during hypoxic stress, thus signifying that it could be a potential drug target for anti-cancer therapies." (PMID 33028364, 2020). "The found phylostratic effect of ploidy-associated c-MYC collaborating with bivalent genes, e.g., both H-RAS (stratum 1) and EGFR (stratum 6) may explain its critical role in cancer initiation when overexpressed, and cancer regression when locked." (PMID 33228223, 2020). "Therefore, this small interfering peptide could be used as a template for the design of therapeutic peptides to inhibit human cancers displaying high MYC expression." (PMID 31944520, 2020). "Indeed, antitumor strategies targeting MYC have offered new cancer therapeutic opportunities." (PMID 32175271, 2020). "Furthermore, MYC can also directly increase CHK1 gene expression in some cancers." (PMID 32859084, 2020). "Indeed, everolimus resistant HCC cells exposed to vitamin D showed a significant downregulation of miR-375 that triggered, in turn, a decreased expression of several oncogenes, such as metadherin, YAP-1 and c-MYC proteins, particularly involved in cell proliferation and cancer drug resistance." (PMID 32560347, 2020). "Indeed in cancer cells, MYC plays a major role in the production of ribosomes, through the direct activation of rRNA synthesis but also of a gene network which includes genes encoding all rRNA processing factors, RPs, and factors implicated in the translation machinery." (PMID 33120992, 2020). "Oncogenic deregulation of MYC is observed in the vast majority (~70%) of human malignancies including breast, colon, cervix, lung, bone, brain, and blood cancers, [101*, 120*, 141*, 163*, 175*, 178*], globally accounting for one-seventh of all cancer deaths [118*]." (PMID 31636382, 2020). "This may reflect a higher dependency on MCL1 and MYC, or apoptotic priming, in cancer cell lines." (PMID 32645016, 2020). "PD-L1 constitutive expression in cancer cells may be due to several oncogenic pathways, including chromosome 9 amplification, PTEN deletions, PI3K/AKT, and EGFR mutations, MYC overexpression, CDK5 disruption, and increased PD-L1 transcription." (PMID 32824016, 2020).
cancer (continued). "Besides translocations, several other mechanisms like gene amplifications and epigenetic alterations of MYC and posttranslational regulation of the MYC protein, in particular its phosphorylation, lead to its constitutive activation in many human cancers including hematological neoplasms." (PMID 33134177, 2020). "MYC takes part in the generation of gap junctions through the up-regulation of Connexin 43 (Cx43), a crucial protein in favoring close interactions between cancer cells and endothelial cells, hence, facilitating extravasation and local survival of metastatic cells." (PMID 33081056, 2020). "c-MYC is a versatile transcription factor that regulates the expression of genes involved in various biological functions such as cell proliferation, apoptosis, differentiation, and metabolism, and its inhibition would be expected to have a huge impact on the cancer transcriptome." (PMID 32429395, 2020). "Therefore, MYC has become an obvious but also difficult therapeutic target for cancer therapy." (PMID 31944520, 2020). "HN1 expression was upregulated in human cancers, which might promote oncogenesis MYC." (PMID 32134197, 2020). "In addition, PRMT5 expression has correlated with MYC or MYCN protein in these cancers." (PMID 31694585, 2019). "Therefore, the combination of EZH2 and IFN-gamma -targeted therapy could represent a potential strategy in the treatment of patients with advanced cancer driven by MYC." (PMID 31366128, 2019). "Likewise, EGFR inhibitor Gefitinib could affect both ATF4 and MYC expression in EGFR mutant cancer cells and xenograft models." (PMID 31221965, 2019). "These previous studies led us to hypothesize that GCN5 may play a role in MYC driven cancers." (PMID 31645904, 2019). "However, when cancers with MYC amplification were removed, the latter correlation disbanded, confirming our hypothesis." (PMID 31383035, 2019). "Therefore, we propose that limiting cellular kynurenine or its downstream targets could present a new strategy to reduce the proliferation of MYC-dependent cancer cells." (PMID 31416966, 2019). "Therefore, c-MYC/miRNAs/target genes axis has emerged as an attractive target for cancer therapy." (PMID 29523159, 2018). "We hypothesized that targeting miR-17 could be effective strategy for MYC driven cancers." (PMID 29464015, 2018). "However, we have suggested recently, that MYC-driven cancers may be generally sensitive to immune therapies, since MYC appears to play a major role in suppressing the immune response against tumors." (PMID 30458889, 2018). "Cancer cells may acquire super enhancers associated with oncogenes such as MYC that are not present in normal cells." (PMID 29428975, 2018). "Thus, different cancer cell lines may have a common set of MTcoR genes that are co-regulated by MYC and the NuA4 complex (represented by Tip60)." (PMID 30108681, 2018). "Accumulating evidence shows that genetic mutations in cancer-driver genes, tumor suppressors, and amplified oncogenes are linked to specific alterations in metabolic pathways in cancer cells, involving proteins such as isocitrate dehydrogenase (IDH), fumarate hydratase (FH), MYC, K-RAS and BRAF." (PMID 30369878, 2018). "Furthermore, the described MYC mutation in ONB has not been verified in the COSMIC database (Catalog of Somatic Mutations in Cancer)." (PMID 29324814, 2018). "Also, it has been suggested that BET inhibition sensitizes PI3K and MYC driven cancer cells to PI3K inhibitor by blocking PI3K pathway reactivation caused by induction and activation of receptor tyrosine kinases (RTKs) through blocking the expression of RTKs45." (PMID 30104685, 2018).
cancer (continued). "We propose that MYC and the NuA4 complex may cooperate to activate the MTcoR panel of genes that function mainly in cell cycle regulation and DNA replication and may play major roles in cancer development." (PMID 30108681, 2018). "Hence the hypothesis that targeting both nucleolar and mitochondrial rRNA synthesis in MYC-overexpressing cancer can have a potential antiproliferative value." (PMID 29435159, 2018). "Thus, identification of a common set of MTcoR panel genes that are co-regulated by MYC and the NuA4 complex in most cancer lines may be valuable in understanding cancer development." (PMID 30108681, 2018). "Interestingly, a prior study showed that in 40% of all human cancers, deregulated MYC expression could be involved in metabolic reprogramming." (PMID 29629339, 2018). "However, the roles of the HAT complexes during MYC function in cancer remains uncharacterized." (PMID 30108681, 2018). "Thus, the MTcoR panel of genes may be targeted for cancer therapy, alone or in combination with targeting of MYC and the NuA4 complex." (PMID 30108681, 2018). "Interestingly, IL-17 is reported to upregulate MYC in some cancer cells." (PMID 28399896, 2017). "Therefore, cancer might become “addicted to c-MYC”, which may warrant the use of c-MYC modulators in the future that can minimize or prevent undesirable side-effects, perhaps in combination with other therapeutic strategies." (PMID 28422055, 2017). "In addition, new strategies that target MYC or its downstream metabolic programs will not only advance the treatment of immunological diseases, but will also hold the promise of impacting immunotherapies in treating cancer and other diseases." (PMID 28245597, 2017). "Under glutamine depletion, cancer cells may undergo MYC-mediated apoptosis." (PMID 28750681, 2017). "Therefore, the discovery of novel lncRNAs-mediated pathway that control MYC activity could, in turn, suggest novel therapeutic windows for the fight against all cancer that rely on MYC expression." (PMID 28704924, 2017). "Thus, our data revealed that Menin regulated cancer cell metabolism via MYC." (PMID 28474697, 2017). "As MYC is known to be deregulated in 30–50% of human malignancies with poor prognosis, our novel discovery may have significant implication for cancer therapy: targeting both Menin and MYC pathways might potentially work for human malignancies with aberrant expression of both MYC and Menin." (PMID 28474697, 2017). "Therefore, c-MYC is a potential target for the control of cancer proliferation." (PMID 28881578, 2017). "However since many cancer cells shows MYC overexpression and/or copy number changes in the MYC gene, the development of agents targeting mitochondrial function may provide a therapeutic option for the treatment of cancer." (PMID 29163823, 2017). "Both AKT and MYC may enhance the Warburg effect in human cancers." (PMID 27231905, 2016). "Finally, we demonstrate here for the first time that KRAS-mutant cancer cell lines expressing elevated levels of MYC show increased sensitivity to several microtubule-interfering agents, opening up new avenues for therapeutic intervention and suggesting new strategies for patient stratification." (PMID 27412232, 2016). "However, the up-regulation bivalent genes is not limited to cancers over-expressing MYC." (PMID 27876760, 2016). "Likewise, several cancers with c-MYC gene amplification tend to be correlated with poor survival." (PMID 27619912, 2016). "Collectively, H19 is one of the most pervasive dysregulated lncRNAs seen in human cancer, and to date it is one of only a few lncRNAs that feeds into a positive feedback loop with MYC, by being transcriptionally upregulated by MYC and post-transcriptionally disinhibiting MYC mRNA degradation." (PMID 27077133, 2015). "Such an approach could help treat MYC-overexpressing cancers." (PMID 26453442, 2015).
cancer (continued). "Because the i-CDK9-induced MYC expression and binding to P-TEFb compensate for P-TEFb's loss of activity, only simultaneously inhibiting CDK9 and MYC/BRD4 can efficiently induce growth arrest and apoptosis of cancer cells, suggesting the potential of a combinatorial treatment strategy." (PMID 26083714, 2015). "Therefore, we screened TF, proto-oncogenes, tumor suppressor genes, and other TAG from the genes adjacent to aberrant DNA methylation sites, of which multiple known cancer related genes, including MYC, DDR1, MEF2C, NDRG2, SIX1, TNFRSF10B and TSGA10, had HyperM phenomena." (PMID 26046465, 2015). "While the role of MYC in cancer has been proved beyond any doubt, the presence of this famous neighbor together with the enigmatic noncoding nature of PVT1 has hampered prompt recognition that another important oncogene coexisted with MYC in the 8q24 risk region." (PMID 25883951, 2015). "Interestingly, MYC, an oncogene which is widely activated in many cancers, bound to ∼45% (635/1386) of the active peaks, while it bound to a significantly smaller proportion of the non-up-regulated peaks (one-sided Fisher's exact test with Bonferroni correction < 0.05)." (PMID 26510915, 2015). "Therefore, targeting MYC can provide a therapeutic window for cancers that have MYC amplification." (PMID 26402672, 2015). "Because MCT1 was reported to be regulated by c-Myc in some cancer cells, and MYC dysregulation was caused by complex translocation or insertion as a late progression event in MM, MCT1 could be induced in advanced MM under the control of c-Myc." (PMID 25909034, 2015). "Because the inhibition of BRD4-mediated recruitment P-TEFb to MYC and other PRGs by JQ1 and iBET-151 can suppress cancer growth and progression, it is tempting to speculate that the direct inhibition of P-TEFb itself will produce a similar or perhaps even more focused effect." (PMID 26083714, 2015). "However if there is no expression of ERα, Bmi1 may be induced by other factors such as E2F1 and MYC, both of which are usually expressed in cancers." (PMID 24559156, 2014). "Moreover, increased levels of MYC are detected in a large number of human cancers." (PMID 24884974, 2014). "Thus, glutamine metabolism may allow cancer cells to adapt to changes in glucose availability by re-programming existing pathways through MYC and the UPR." (PMID 25339305, 2014). "Therefore, understanding the therapeutic effects of targeting multiple MYC-mediated metabolic pathways may be crucial for the treatment of cancer." (PMID 24884974, 2014). "Thus, it is important to understand why JQ1 is effective in only certain MYC-dependent cancers, which may ultimately determine clinical efficacy of this compound in patients." (PMID 24466310, 2014). "Thus, MYC induced cell death in cancer cells warrants further elucidation." (PMID 25339305, 2014). "Although c-MYC-specific adoptive T-cell therapy is still at its infancy, it may represent on a long run a highly attractive and promising novel tool that may complement classical anti-cancer chemotherapy." (PMID 24130880, 2013). "Thus, MYC deregulation may result in alterations in different biological pathways involved in cancer initiation and progression." (PMID 23717612, 2013). "Furthermore, the E2F and the miR-17-92 cluster could form FBLs, and in the cancer regulation network, FBLs involving miR-17-92, E2F and MYC have been reported." (PMID 24200043, 2013). "Because regulation of MYC by cohesin is conserved in several species, and MYC regulation is thought to be central to mechanisms of tumorigenesis in several types of cancer, it was of considerable interest to determine whether cohesin-mediated regulation of MYC is relevant to human cancers." (PMID 23145106, 2012).